NR3C2 (nuclear receptor subfamily 3 group C member 2)
Diseases named in the same sentence as NR3C2 in open-access papers (continued):
Sharing a sentence is not in itself a finding about the gene and the disease.
sleep disorder (2 papers, 2022 to 2024). A change from the patient's baseline sleeping pattern, in the hours slept and/or an alteration/dysfunction in the stages of sleep. "Methylation of the promoter regions of the placental NR3C2 were lower in the mothers with sleep disorder (Group 1, Group 2, and Group 3) than that of the group without sleep disorder (Group 4)." (PMID 35321658, 2022). "Furthermore, we found maternal sleep disorder in the third trimester of pregnancy results in decreased NR3C2 promoter methylation and increased MNTR1B promoter methylation." (PMID 35321658, 2022). "A zebrafish NR3C2 KO model has confirmed features of ASD, including social behavior deficits and sleep disorders." (PMID 39596384, 2024). "The methylation of NR3C2 and MNTR1B were similarly altered in the placenta of mother with postpartum sleep disorders." (PMID 35321658, 2022). "Level of NR3C2 methylation was lower and GR expression was higher in the placenta of mothers with sleep disorder extend from the third trimester to postpartum than in mothers without sleep disorder." (PMID 35321658, 2022).
cervical cancer (1 paper, 2021). A primary or metastatic malignant neoplasm involving the cervix. "Several studies have indicated that NR3C2 can be a tumor suppressor gene in cancers such as colorectal, pancreatic, and cervical cancers." (PMID 34737698, 2021).
colorectal adenoma (1 paper, 2021). An adenoma that arises from the colon or rectum. "Notably, six DE-TFs, DACH1, GTF2IRD1, MEIS2, NR3C2, SOX9, and SPIB, were identified as having a dynamic signature along the colorectal adenoma-carcinoma sequence." (PMID 34094897, 2021).
conduction disorders (1 paper, 2022). "There are no studies about conduction disorders after AMI and NR3C2 gene polymorphisms." (PMID 36612333, 2022).
corticotroph adenoma (1 paper, 2022). "Expression of both miRNAs is higher in corticotroph adenomas causing CD which corresponds to the lower expression of the NR3C2 gene in these tumors as compared to SCAs." (PMID 35270010, 2022). "We determined the expression levels of NR3C1 and NR3C2 in corticotroph adenomas with qRT-PCR." (PMID 35270010, 2022). "AtT-20 cells, which are the only available cell line model of corticotroph adenoma, do not express MR receptor, thus the procedure of experimental validation of the role of miRNA in NR3C2 silencing is not applicable." (PMID 35270010, 2022).
Dent disease (1 paper, 2023). Dent disease is a rare genetic renal tubular disease characterized by manifestations of proximal tubule dysfunction. "A variant in CLCN5 was found in one patient (Dent disease), and in NR3C2 in another patient (Geller syndrome)." (PMID 37537162, 2023).
Failure to thrive (1 paper, 2021). Failure to thrive (FTT) refers to a child whose physical growth is substantially below the norm. "Autosomal dominant PHA1 (ADPHA1, OMIM #177735) is caused by inactivating mutations in the NR3C2 gene, which encodes the mineralocorticoid receptor, and it can lead to renal salt-wasting, dehydration, and failure to thrive during infancy." (PMID 34943285, 2021).
hippocampal atrophy (1 paper, 2025). "In longitudinal analyses, the interaction of NR3C2 gene-body CpG site cg07275757 x GDS was nominally associated with differences in hippocampal atrophy in both AIBL and ADNI cohorts." (PMID 40964007, 2025). "Higher methylation at the two sites, cg00328411 and cg27225476, both located within NR3C2 gene-body, was associated with an increased rate of hippocampal atrophy in both the AIBL and ADNI cohorts." (PMID 40964007, 2025).
invasive breast carcinoma (1 paper, 2021). A carcinoma that infiltrates the breast parenchyma. "Therefore, in this study, we used bioinformatics to broadly investigate and obtain a deeper understanding of the prognostic significance between NR3C2 and invasive breast carcinoma (BRCA)." (PMID 33564687, 2021). "However, the clinical significance of NR3C2 is unclear in invasive breast carcinoma (BRCA)." (PMID 33564687, 2021).
keloid (1 paper, 2024). An irregularly shaped, elevated mark on the skin caused by deposits of excessive amounts of collagen during wound healing. "Furthermore, we found that 2 TFs, NR3C2 and YY1, are less expressed in keloid and AD samples than in the control group of GSE158395 and GSE12121." (PMID 38476235, 2024). "Finally, two TFs of CCR5, NR3C2 and YY1, were identified, both of which were downregulated in keloid and AD tissues." (PMID 38476235, 2024).
lymph node metastasis (1 paper, 2020). "The expressions of miR-224 and miR-147b were validated to be upregulated, while WDR82, PRPF4B and NR3C2 were downregulated in lymph node metastasis samples of TCGA datasets compared with non-metastasis samples." (PMID 33282547, 2020).
mesenchymal tumors (1 paper, 2021). "Notably, proneural tumors showed lower NR3C2 expression than classical or mesenchymal tumors." (PMID 34769089, 2021).
metastatic carcinoma (1 paper, 2023). A carcinoma which has spread from the original site of growth to another anatomic site. "But NR3C2 was significantly downregulated in three VEGFR‐2 high expressions CRC tissues: right‐sided, poorly differentiated and lymph node metastatic carcinomas." (PMID 36950803, 2023).
myeloma (1 paper, 2023). "Despite that NR3C2 mRNA is present in all myeloma cell lines, MR protein levels were hardly detectable via Western analyses in both U-266 and L-363 cells, indicating low MR protein expression in the latter cell lines." (PMID 37578563, 2023).
pituitary tumor (1 paper, 2023). A benign or malignant neoplasm affecting the pituitary gland. "Due to a weak relationship with patients characteristics it is difficult to indicate any clinical usefulness of testing NR3C1 or NR3C2 expression but our data support the clinically relevant roles of the receptors expression levels in functioning corticotroph pituitary tumors." (PMID 37065760, 2023).
tumor (58 papers, 2009 to 2025). "In LGG, lower expression of NR3C2 is linked to worse survival, suggesting that its down regulation furthers tumor progression." (PMID 34769089, 2021). "Through bioinformatics analysis, we observed that the expression level of NR3C2 is significantly lower in tumor tissues compared to normal tissues." (PMID 40229278, 2025). "The expression levels of pivotal regulatory genes (CDCA8, AURKA, and PLK1) were significantly higher in tumor samples than in control samples, whereas NR3C2 was significantly downregulated in cancerous tissues." (PMID 41357242, 2025). "Recent international and domestic studies have highlighted the anti-cancer role of NR3C2 in various tumor types." (PMID 40229278, 2025). "We then compared the expression of NR3C2 in CRC tumours and adjacent normal tissues in each of the five data sets." (PMID 36950803, 2023). "We discovered that overexpression of NR3C2 inhibits tumour progression by suppressing glucose metabolism and AMPK expression." (PMID 36950803, 2023). "The mRNA levels of NR3C2 in CRC tumours were significantly decreased compared to matched paracancerous tissues." (PMID 36950803, 2023). "Gene expression levels of NR3C1 and NR3C2 coding for GR and MR, respectively, were determined with qRT-PCR in the two tumor types." (PMID 37065760, 2023). "IHC staining results showed that the protein levels of NR3C2 were also decreased in CRC tumours compared to paracancerous tissues." (PMID 36950803, 2023). "The GEPIA database was also used to compare the expression of NR3C2 in CRC tumours and paracancerous tissues." (PMID 36950803, 2023). "The expression of NR3C2 in CRC tumours and paired paracancerous tissues of 71 CRC patients and five CRC cell lines was detected by western blotting, immunohistochemistry and real‐time reverse‐transcription PCR." (PMID 36950803, 2023). "The expression of NR3C2 was significantly decreased in CRC tumours compared to paracancerous tissues, which was correlated with distant metastasis, poor prognosis and advanced stages of CRC patients." (PMID 36950803, 2023). "This includes, for example, adherens junctions important for intestinal permeability (Vdr), intestinal cortisol production (Lrh1), tumor-suppressive functions (Nr3c2), and suppression of CRC aggressiveness (Esrrg)." (PMID 36142324, 2022). "Recent studies have shown that NR3C2 can inhibit the proliferation, invasion, and migration of certain tumor cells." (PMID 33564687, 2021). "In consideration of the significant enrichment Module1 with immune responses, NR3C2 was suggested to play a role in the tumor immune microenvironment." (PMID 34094897, 2021). "Gene set enrichment analysis (GSEA) and tumor immune infiltration analysis were conducted to explore the molecular mechanism of NR3C2 in BRCA." (PMID 33564687, 2021). "NR3C2 has been reported to present tumor-repressing behaviors in multiple cancers, but it has never been investigated in GBM." (PMID 32280303, 2020). "In our ceRNA network, low PART1 expression reduced levels of NR3C2 mediated by mir-301b, and reduced expression of NR3C2 promotes tumor cell proliferation, metastasis and epithelial-to-mesenchymal transition." (PMID 30755833, 2019). "This list includes known tumour suppressors such as the nuclear receptor NR3C2, the helix-loop-helix transcription factor TCF21, and SMARCA2 (also known as BRM), a member of the SNF/SWI chromatin remodelling complex." (PMID 27562343, 2016). "Among them, NR3C2 was demonstrated to be correlated with poor prognosis and tumour staging of CRC, which may serve as a therapeutic target." (PMID 36950803, 2023). "As reported, miR-301b may be a tumor-promoting miRNA in BRCA, and miR-301b/NR3C2 axis mediated tumor development from cell proliferation and migration." (PMID 37098532, 2023). "A genome-wide lethality screening in NSCLC reported that NR3C2 might be a potential tumor-suppressing gene." (PMID 36793597, 2023).
tumor (continued). "Notably, the expression of NR3C2 was significantly decreased in CRC tumours than in adjacent normal tissues in all five data sets." (PMID 36950803, 2023). "CREBRF and NR3C2 transcriptional factors are considered tumor suppressors." (PMID 36358691, 2022). "NR3C2 has been reported as a tumor suppressor gene in certain tumors." (PMID 33564687, 2021). "Interestingly, although GR and MR are both involved in the response to glucocorticoids, to our knowledge, there is no data on NR3C2 or MR protein expression in CD-causing tumor available to date." (PMID 37065760, 2023). "We used mice corticotroph tumor AtT-20/D16v-F2 cells for in vitro experiment and initially verified whether these cells do express Nr3c1 and Nr3c2 genes using deposited RNAseq data from a previous experiment on AtT-20 cells (GSE132324; Gene Expression Omnibus) and qRT-PCR." (PMID 35270010, 2022). "NR3C2 is considered to be a tumour suppressor and may be correlated with T cell activation." (PMID 34288383, 2021). "Tumor tissues exhibited significant upregulation of CDCA8, AURKA, and PLK1, whereas NR3C2 was notably downregulated (p < 0.0001)." (PMID 41357242, 2025). "We found that NR3C2 was downregulated in CRC and correlated with not only tumour stages but also distant metastasis." (PMID 36950803, 2023). "The results of rock curve analysis demonstrated that the differential expression of SYNPO2, NR3C2, and CCL28 had a major role in distinguishing tumour tissues from borderline samples." (PMID 38081950, 2023). "In CD patients NR3C1 and NR3C2 levels were negatively correlated with morning plasma ACTH levels and tumor size." (PMID 37065760, 2023). "While CREBRF suppresses tumor progression by downregulating CREB3 and ATG5, NR3C2 inhibits cancer cell survival and migration through repression of β-catenin and c-Myc." (PMID 36358691, 2022). "For the first time, we identified that miR124-3p and miR766-3p attenuate expression of CREBRF and NR3C2, respectively, in HNSCC, which promotes aggressive tumor behavior by inducing the signaling axes CREB3/ATG5 and β-catenin/c-Myc." (PMID 36358691, 2022). "Studies have shown that the anti-tumor effect of 5-FU has a certain correlation with PTGS2, NR3C2, CA2 and MMP1." (PMID 34125845, 2021). "Nuclear receptor subfamily 3, group C, member 2 (NR3C2), a tumor suppressor, has a positive correlation with survival rate and can inhibit epithelial mesenchymal transition." (PMID 34485124, 2021). "Compared to normal samples, the expression of E2F2, FOXJ1, EMX1, PAX7, NKX6-1, FOXD1, and ZNF552 was significantly higher (P < 0.05) and the expression of MSX1, STAT4, NR3C2, and EGR3 was significantly lower in tumor samples (all P < 0.05)." (PMID 33688372, 2021). "For example, in HCC, miR-885-3p and miR-766 played a role in tumor progression by targeting TIGAR and NR3C2, respectively." (PMID 33221765, 2020). "qRT-PCR analysis of all enrolled patient samples (246 in total), we demonstrated that the RNA expression of NR3C2 in tumor tissues is markedly lower than in adjacent non-cancerous tissues." (PMID 40229278, 2025). "The Western blot analysis of 32 randomly selected samples indicated a noteworthy reduction in the protein expression of NR3C2 in tumor tissues compared to adjacent non-cancerous tissues." (PMID 40229278, 2025). "The analysis of NR3C2 expression in samples from enrolled patients, revealed that it in tumor tissues was lower than that in paired adjacent non-cancerous tissues by IHC." (PMID 40229278, 2025).
tumor (continued). "Although PKIA and NR3C2 are not well understood in the context of TNBC, emerging data from other cancer types indicate they may have important roles in kinase signaling and tumor biology, necessitating further functional studies." (PMID 41017855, 2025). "In addition, the expression of CCR4, MX2, and NR3C2 were significantly correlated with the stromal score, immune score, ESTTIMATE score, and tumor purity." (PMID 35619698, 2022). "According to these results, the expression levels of NR3C2, KLF4, CASZ1, FOXD2, ATOH1, and RORC reduce in CRC and may function as tumor suppressors." (PMID 36344988, 2022). "Furthermore, miR-1204 targeted and inhibited Nuclear receptor subfamily 3 group C member 2 (NR3C2), a tumor suppressor gene in GBM cells." (PMID 32280303, 2020). "Besides, NR3C2 was associated with CRC overall survival and tumour stage categorized into stages I and II but not with other pathophysiological characteristics in a study including 30 CRC patients." (PMID 36950803, 2023). "Specifically, the NR3C2, ANPEP, and FCGRT genes were significantly upregulated in tumor tissues, while PIK3R1, MME, SCD, and SERPINE1 genes were notably downregulated." (PMID 41011246, 2025). "Unlike NR3C2, HSD11B2 expression did not significantly change between GBM and normal tumor." (PMID 34769089, 2021). "The top differentially expressed transcripts between tumor and non-tumor were TPX2, DCBLD2 and ANLN which were significantly increased in tumors (T∶N ratio>2.0, P<0.01), and CDO1, DPEP1, C7, ALDH1A1 and NR3C2 which were significantly decreased in tumors (T∶N ratio<0.2, P<0.01)." (PMID 22363658, 2012). "Similarly, the expression level of NR3C2 was not correlated with age and gender but importantly negatively related to T stage, N stage, M stage, TNM stage, and tumor G grade." (PMID 35145542, 2021).
cancer (47 papers, 2009 to 2025). A tumor composed of atypical neoplastic, often pleomorphic cells that invade other tissues. "NR3C2 (nuclear receptor subfamily 3, group C, member 2) is a transcription factor and encodes mineralocorticoid receptor protein, which inhibits cancer angiogenesis." (PMID 36110953, 2022). "We also analysed and compared NR3C2 gene expression in cancer and normal thyroid tissue from the same patient (a total of 29 patients)." (PMID 38255827, 2024). "One bioinformatic study revealed that NR3C2 was downregulated in six types of cancers including bladder, breast, colon, head and neck, liver and prostate." (PMID 36950803, 2023). "miR124-3p affects the CREBRF-ATG5/CREB3 axis, while miR766-3p affects the NR3C2-c-Myc/β-catenin axis; therefore, the combined targeting of these two miRNAs complement each other and shows an additive effect on sensitizing cancer cells to chemo-radiotherapy." (PMID 36358691, 2022). "In contrast, such cross-contour interaction links are clearly visible in eXamine (e.g. the transition from Kras in Pathways in cancer to Nr3c2 outside of Pathways in cancer)." (PMID 25002203, 2014). "In addition to CRC, NR3C2 was also downregulated in 15 types of cancer tissues such as bladder, breast and kidney." (PMID 36950803, 2023). "In summary, our results indicated that NR3C2 expression is downregulated in more malignant tumors." (PMID 34769089, 2021). "Instead, the Pathways in cancer genes Kras, Met, Figf, Hgf, Fgf7, Ctnnb1 and Tcf7l1, and directly interacting genes Nr3c2 and Csnk2a1 may lead to new insights in US28-mediated signaling and ultimately the oncomodulatory role of HCMV." (PMID 25002203, 2014). "A total of 20 target mRNAs of three miRNAs were predicted, among which seven target mRNAs—ASAP3, BCL2L2, LMF1, PPM1L, PTPN21, SLC18A2, and NR3C2—had prognostic value; PRKACB, PDCD4, RPS6KA5, and BCL2L2 were enriched in the miRNA cancer pathway." (PMID 36829221, 2023). "In another study, MIF was also demonstrated to restrict nuclear receptor subfamily 3 group C member 2 (NR3C2), which negatively regulates EMT-promoting factors in cancer cells." (PMID 32756339, 2020). "Additionally, differences were observed in NR3C2, ATR, ALK, EPHB6, SPEN in intermediate cells (I-1 to I-8) relative to the cancer cells." (PMID 35951662, 2022). "Interestingly, NR3C2, PGR, RORA were differentially expressed in all 16 cancer types, while HNF4G was differentially expressed in only 5/16 cancers (31.3%)." (PMID 32024906, 2020). "Although the interaction relationships between hsa-miR-224 and PRPF4B, as well as between hsa-miR-31 and NR3C2/PPP6C have not been experimentally demonstrated previously, the function studies on these target genes in cancers may indirectly reveal the possible roles of hsa-miR-224 and hsa-miR-31." (PMID 33282547, 2020).
neurodevelopmental disorder (3 papers, 2021 to 2024). A behavioral and cognitive disorder with onset during the developmental period that involves impaired or aberrant development of intellectual, motor, or social functions. "We next examined whether dhx30-deficient zebrafish exhibit abnormal sleep-wake activity and social behaviors, similar to those recently observed in a zebrafish model of the NR3C2-related neurodevelopmental disorder." (PMID 34020708, 2021).
NR3C2 also shares sentences with these, for which no sentence is quoted: heart failure (359 papers); chronic kidney disease (142); Hyperkalemia (122); type 2 diabetes (72); cardiovascular disease (62); diabetic kidney disease (62); kidney disease (61); Hypokalemia (57); endothelial dysfunction (50); cardiac hypertrophy (42); primary aldosteronism (37); atrial fibrillation (35); chronic heart failure (34); Insulin resistance (31); coronary artery disease (29); renal fibrosis (29); atherosclerosis (25); resistant hypertension (25); renal failure (24); hyperaldosteronism (21); cardiac disease (19); essential hypertension (19); Myocardial fibrosis (19); Stroke (19); Arrhythmia (18); Gynecomastia (18); mineralocorticoid excess (18); cardiomyopathy (17); infection (17); acute myocardial infarction (16).
A further 303 diseases each share a sentence with NR3C2 in 16 papers or fewer.